WDR4 (WDR4 tRNA N7-guanosine methyltransferase non-catalytic subunit)
Diseases named in the same sentence as WDR4 in open-access papers (continued):
Sharing a sentence is not in itself a finding about the gene and the disease.
Galloway-Mowat syndrome (5 papers, 2023 to 2025). Galloway syndrome is characterized by the association of nephrotic syndrome and central nervous system anomalies. "Mutation of WDR4 is causative for a heterogeneous group of microcephalic primordial dwarfism and Galloway-Mowat syndrome." (PMID 36733406, 2023). "In addition, mutations in WDR4 also cause several human neurodevelopmental defects, including Galloway-Mowat syndrome (GAMOS) and microcephaly." (PMID 39723662, 2025).
asthenozoospermia (4 papers, 2021 to 2023). "In conclusion, our results suggest a critical role of WDR4 gene variant as well as protein expression in asthenozoospermia." (PMID 34442404, 2021). "The effects of WDR4 variants on human male infertility (oligozoospermia, asthenozoospermia, teratozoospermia) were investigated." (PMID 34442404, 2021). "In the genetic association analysis, rs465663, an intronic variant of WDR4, was associated with asthenozoospermia." (PMID 34442404, 2021). "One study demonstrated that the WDR4 gene rs465663 polymorphism might predispose to asthenozoospermia." (PMID 36733406, 2023). "This study offers important information related to genetic variants and expression level of the WDR4 which might affect infertility in the cases of asthenozoospermia." (PMID 34442404, 2021).
breast carcinoma (3 papers, 2023 to 2025). "The inhibition of WDR4 was shown to significantly impair breast cancer progression both in vitro and in vivo." (PMID 40496210, 2025).
hepatoblastoma (3 papers, 2022 to 2023). Hepatoblastoma (HB) is a malignant hepatic tumor and is the most common pediatric liver cancer. "And then, an unconditional logistic regression analysis was performed to assess the association between WDR4 gene polymorphisms and hepatoblastoma risk." (PMID 36186903, 2022). "In the current study, we analyzed five potential functional WDR4 gene SNPs with 313 cases and 1446 controls, and found that Chinese girls bearing two or more risk genotypes were more likely to develop hepatoblastoma than girls with few risk genotypes." (PMID 36186903, 2022). "They found that female carriers with 2-5 risk genotypes were more vulnerable to hepatoblastoma, demonstrating that the WDR4 gene polymorphism may be a risk factor for hepatoblastoma." (PMID 37283791, 2023). "Overall, we demonstrated that the presence of two more selected WDR4 gene SNPs might increase the risk of hepatoblastoma in girls." (PMID 36186903, 2022). "However, in combination, two or more WDR4 gene polymorphisms significantly conferred increased hepatoblastoma risk in girls." (PMID 36186903, 2022). "Our findings may encourage more genetic association studies to discover significant polymorphisms in the WDR4 gene for hepatoblastoma." (PMID 36186903, 2022). "We performed a case-control study (313 cases vs. 1446 controls) to investigate whether genetic variants in the WDR4 gene influence hepatoblastoma susceptibility in the Chinese Han nationality." (PMID 36186903, 2022). "Our results indicate WDR4 as a hepatoblastoma predisposition gene." (PMID 36186903, 2022). "Our results provided evidence that WDR4 may be a hepatoblastoma susceptibility gene." (PMID 36186903, 2022). "In vitro and in vivo functional analyses are warranted to explore the implication of WDR4 in hepatoblastoma tumorigenesis in the future direction." (PMID 36186903, 2022). "Our group has previously reported that many genetic variants of genes encoding RNA m6A and m7G methyltransferase, demethylase, and m6A-reading proteins confer hepatoblastoma susceptibility, including METTL3, METTL4, AlkB homolog 5 (ALKBH5), FTO, YTHDC1, YTHDF1, WTAP, WDR4, and METTL1." (PMID 37531210, 2023). "Finally, biologically relevant evidence is lacking that WDR4 has a role in hepatoblastoma pathogenesis due to the novelty of this gene." (PMID 36186903, 2022).
microcephalic primordial dwarfism (3 papers, 2022 to 2025). Primordial dwarfism with microcephaly. "We further analyzed primary fibroblasts derived from the Seckel syndrome-like patients carrying the R84H variant, which display a markedly reduced expression of WDR4." (PMID 39251572, 2024). "WDR4, a functional methyltransferase in m7G methylation complex with METTL1, is frequently associated with neurodevelopmental disorders, including microcephalic primordial dwarfism and Down syndrome." (PMID 41149057, 2025). "Mutations, knockouts, and overexpression of m7G-related genes, such as WD repeat domain 4 (WDR4), lead to microcephalic primordial dwarfism, Nervous system damage, and impairment of learning and memory abilities." (PMID 36468039, 2022).
colon cancer (2 papers, 2023 to 2024). "We further assess the effect of METTL1 and WDR4 on the immune microenvironment in colon cancer by ssGSEA algorithm." (PMID 39440054, 2024). "We also assessed the effect of METTL1 and WDR4 on the immune microenvironment in colon cancer." (PMID 39440054, 2024).
male infertility (2 papers, 2021 to 2023). The inability of the male to effect fertilization of an ovum after a specified period of unprotected intercourse. "Here, we identified variants of the WDR4 gene that related to male infertility." (PMID 34442404, 2021).
sarcoma (2 papers, 2023 to 2024). A usually aggressive malignant neoplasm of the soft tissue or bone. "WDR4 and race were also identified as independent risk factors for sarcomas." (PMID 36816047, 2023). "Moreover, AGO2, EIF4G3, NCBP1, and WDR4 were potential risk factors for DSS in sarcomas." (PMID 36816047, 2023). "Sarcoma patients were divided into two groups according to the risk scores, survival status, and the expression of EIF4A1, EIF4G3, NCBP1, and WDR4." (PMID 36816047, 2023). "The correlation between the expression of prognostic m7GRGs (EIF4A1, EIF4G3, NCBP1, WDR4) and immune infiltration in sarcomas was investigated using the TIMER database and TCGA database." (PMID 36816047, 2023). "An effective nomogram was constructed to predict the 1-year, 3-year, and 5-year survival rates of patients with sarcoma, indicating that WDR4 and race\ have a significant influence on the prevalence and prognosis of sarcomas." (PMID 36816047, 2023). "The results of the univariate and multivariate analyses revealed that WDR4 expression and race were independent factors affecting the prognosis of sarcoma patients." (PMID 36816047, 2023). "Risk score = (0.1472) *EIF4A1 + (0.4087)*EIF4G3 (−0.2538)*NCBP1 + (0.6578)*WDR4 was applied to the calculation of OS in sarcoma patients." (PMID 36816047, 2023). "Theoretically, miRNAs that bind to high expression EIF4A1, EIF4G3, NCBP1, and WDR4 should be down regulated in sarcomas and show poor prognosis." (PMID 36816047, 2023). "Sarcoma patients were divided into two groups based on the distribution of risk scores, survival status, and expression of EIF4G3 and WDR4 and the risk score = (0.1036)*EIF4G3 + (0.5255)*WDR4 was applied to the calculation of DSS." (PMID 36816047, 2023). "Besides, we constructed a prognostic model that consists of EIF4A1, EIF4G3, NCBP1, and WDR4 m7GRGs for predicting the survival likelihood of sarcoma patients." (PMID 36816047, 2023). "WDR4-hsa-miR-195-5p might represent a critical pathway that mediated the incidence and development of sarcomas, incorporating the findings of correlation and survival study." (PMID 36816047, 2023). "TMB and MSI scores of sarcomas were dramatically enhanced with the increase of EIF4G3, NCBP1, and WDR4 expression according to our findings." (PMID 36816047, 2023). "Patients with sarcoma who had high levels of EIF4A1, EIF4G3, NCBP1, and WDR4 exhibited a lower OS rate." (PMID 36816047, 2023). "According to TIMER data, EIF4G3, and NCBP1 were negatively connected with CD4+ T cells and dendritic cells, however, EIF4A1 and WDR4 were not substantially correlated with immune cell infiltration in sarcomas." (PMID 36816047, 2023). "However, EIF4A1 and WDR4 were not significantly correlated with immune cell infiltration in sarcomas." (PMID 36816047, 2023).
Cerebellar atrophy (1 paper, 2023). Cerebellar atrophy is defined as a cerebellum with initially normal structures, in a posterior fossa with normal size, which displays enlarged fissures (interfolial spaces) in comparison to the foliae secondary to loss of tissue. "Third, patients carrying Wdr4 variants exhibit brain phenotypes other than cerebellar atrophy and locomotion defects." (PMID 36681682, 2023). "Thus, our mouse model is suitable for studying the underlying mechanisms of cerebellar atrophy caused by Wdr4 variants and for testing potential therapeutic strategies for these patients." (PMID 36681682, 2023). "Patients with mutations of WDR4, a substrate adaptor of the CUL4 E3 ligase complex, develop cerebellar atrophy and gait phenotypes." (PMID 36681682, 2023).
cholangiocarcinoma (1 paper, 2022). A carcinoma that arises from the intrahepatic biliary tree (intrahepatic cholangiocarcinoma) or from the junction, or adjacent to the junction, of the right and left hepatic ducts (hilar cholangiocarcinoma). "Upregulated METTL1 and WDR4 promoted the translation of oncogenic transcripts depending on m7G-modified tRNA to promote intrahepatic cholangiocarcinoma progression." (PMID 36396627, 2022).
ciliopathy (1 paper, 2024). A genetic disorder of the cellular cilia or the cilia anchoring structures, the basal bodies, or of ciliary function. "Because of these unanticipated findings, we questioned the importance of the functional interaction of WDR4 with METTL1 regarding the ciliopathy-like phenotypes in fish and cells." (PMID 39251572, 2024).
cold (1 paper, 2023). "Our results show that the typical m7G methylation-related genes, METTL1, and WDR4, are more highly expressed in high-risk and cold tumors compared to the other two subgroups." (PMID 37147395, 2023).
epilepsy (1 paper, 2024). A brain disorder characterized by episodes of abnormally increased neuronal discharge resulting in transient episodes of sensory or motor neurological dysfunction, or psychic dysfunction. "Additional seizure- and epilepsy-associated proteins identified in PTE+ and PTE− cortex and hippocampus include Scnb1, Isca2, Wdr4, and Dkc1." (PMID 38474127, 2024).
Esophageal Carcinoma (1 paper, 2022). A primary or metastatic malignant neoplasm involving the esophagus. "Especially, METTL1 and WDR4 showed dramatic upregulation in Esophageal Carcinoma (TCGA-ESCA)." (PMID 35304469, 2022).
Huntington disease (1 paper, 2025). Huntington disease (HD) is a rare neurodegenerative disorder of the central nervous system characterized by unwanted choreatic movements, behavioral and psychiatric disturbances and dementia. "We selected HIP1R, ATP1B1, and WDR4 to validate the proteomic results, as they are associated with Huntington’s disease, neuronal axon regeneration, and neurological disorders, respectively." (PMID 40001624, 2025).
Infertility (1 paper, 2021). "The results further support the possibility that lower expression of WDR4 in males resulted in infertility." (PMID 34442404, 2021).
leukemia (1 paper, 2023). A malignant (clonal) hematologic disorder, involving hematopoietic stem cells and characterized by the presence of primitive or atypical myeloid or lymphoid cells in the bone marrow and the blood. "In genetically engineered mouse models, the WDR4/Promyelocytic leukemia (PML) axis elevates intratumoral Tregs and M2-like macrophages and reduces CD8+ T cells to promote lung tumor growth." (PMID 36816047, 2023).
lymph node metastasis (1 paper, 2025). "Both METTL1 and WDR4 levels were positively correlated with lymph node metastasis in PTC patients." (PMID 40360483, 2025). "By analyzing the protein expression of METTL1, WDR4, and TNF-α in PTC tumor tissues, we found that PTC tissues from patients with lymph node metastasis had higher METTL1, WDR4, and TNF-α expression than those from patients without lymph node metastasis did." (PMID 40360483, 2025).
male fertility (1 paper, 2021). A fertility quality of inhering in a male by virtue of the bearer's disposition to initiate, sustain, or support reproduction. "However, it is unclear whether WDR4 is associated with clinical manifestations of male fertility in human." (PMID 34442404, 2021).
metastatic cancer (1 paper, 2023). A carcinoma which has spread from the original site of growth to another anatomic site. "Moreover, higher WDR4 expression was observed in metastatic cancer tissues than in nonmetastatic cancer tissues of patients." (PMID 37783676, 2023).
Obesity (1 paper, 2025). Accumulation of substantial excess body fat. "However, the regulatory role and underlying mechanisms of WDR4 in obesity remain unexplored." (PMID 41292047, 2025). "This study reveals that WDR4 was downregulated in the context of obesity, and overexpression of WDR4 induced brown fat activation by enhancing mitophagy, highlighting its critical role in regulating mitochondrial homoeostasis and adipose tissue metabolism." (PMID 41292047, 2025). "Our findings not only reveal the critical role of WDR4 in adipocyte browning but also provide novel insights for understanding obesity and related metabolic disorders." (PMID 41292047, 2025). "In all, the tRNA m7G methyltransferase complex protein METTL1/WDR4 were downregulated in HFD-induced obesity mice." (PMID 41292047, 2025). "This study revealed that WDR4-mediated m7G modification is involved in BAT activation, providing novel insights into the role of epitranscriptomic regulation in adipose tissue metabolism and obesity." (PMID 41292047, 2025). "Our findings demonstrated that WDR4 drives mitophagy through enhancing BMP8B expression by increasing its translation efficiency by tRNA m7G modification, thereby promoting adipocyte browning and improving metabolic health in the context of obesity." (PMID 41292047, 2025).
osteoarthritis (1 paper, 2024). A noninflammatory degenerative joint disease occurring chiefly in older persons, characterized by degeneration of the articular cartilage, hypertrophy of bone at the margins and changes in the synovial membrane. "Apart from its role in the nervous systems, recent research has identified WDR4 expression as a significant hub gene in the context of osteoarthritis, showing significant upregulation in osteoarthritis tissues." (PMID 38943267, 2024).
Primary microcephaly (1 paper, 2024). Head circumference below 2 standard deviations below the mean for age and gender at birth. "The WD repeat-containing protein 4 (WDR4) has repeatedly been associated with primary microcephaly, a condition of impaired brain and skull growth." (PMID 39251572, 2024).
promyelocytic leukemia (1 paper, 2022). "Mechanistically, WDR4 was identified as one kind of oncogenic protein, which regulates promyelocytic leukemia through ubiquitination negatively and promotes pulmonary tumor advance via cultivating a metastatic and immunological suppressive neoplastic microenvironment." (PMID 36118897, 2022).
rectal adenocarcinoma (1 paper, 2024). "WDR4 gene expression was found to be down-regulated in advanced renal papillary carcinoma but constant in advanced rectal adenocarcinoma and GC in one study." (PMID 38436027, 2024). "WDR4 expression was also found to be a protective factor in rectal adenocarcinoma in the corresponding OS outcome study." (PMID 38436027, 2024).
Renal cyst (1 paper, 2024). A fluid filled sac in the kidney. "Increased frequency of renal cysts in embryos with reduced Wdr4 suggests physiological relevance of this ciliogenesis defect." (PMID 39251572, 2024).
viral infection (1 paper, 2021). "One type of m7G writer, WDR4, was downregulated after viral infection, as shown in two of six experiments." (PMID 34502037, 2021).
Williams-Beuren syndrome (1 paper, 2024). "Complexes involving METTL1 and WD repeat domain 4 (WDR4) as well as Williams-Beuren syndrome chromosome region 22 and tRNA methyltransferase activator subunit 11-2 (TRMT112) catalyze these modifications." (PMID 38798700, 2024).
Wilms tumor (1 paper, 2023). An embryonal neoplasm characterized by the presence of epithelial, mesenchymal, and blastema components. "In brief, our study demonstrated that the rs6586250 C > T polymorphism of the WDR4 gene was significantly associated with Wilms tumor." (PMID 37283791, 2023). "In brief, this large, five-center epidemiological study demonstrated a significant correlation between functional SNPs in the WDR4 gene and Wilms tumor susceptibility." (PMID 37283791, 2023). "In conclusion, these data suggested that functionally selected SNPs in the WDR4 gene have a significant impact on increased risk for Wilms tumor." (PMID 37283791, 2023). "In the current study, we demonstrated that the selected rs6586250 C > T polymorphism of the WDR4 gene was significantly associated with an increased risk of Wilms tumor." (PMID 37283791, 2023). "To date, no research has investigated the association between functional single nucleotide polymorphisms (SNPs) in the WDR4 gene and Wilms tumor susceptibility." (PMID 37283791, 2023). "Moreover, we tried to further explore the possible mechanism of how significant SNPs of WDR4 conferred susceptibility to Wilms tumor." (PMID 37283791, 2023). "Therefore, further functional experiments are warranted to explore the unique mechanism by which SNPs in the WDR4 gene affect Wilms tumor susceptibility." (PMID 37283791, 2023). "However, no studies involving the relationship between genetic variants in the WDR4 gene and Wilms tumor risk have been reported thus far." (PMID 37283791, 2023). "In addition, unconditioned logistic regression analysis was performed, odds ratios (ORs) and 95% confidence intervals (CIs) were used to assess the association between WDR4 gene SNPs and Wilms tumor susceptibility as well as the strength of the associations." (PMID 37283791, 2023). "We performed a large case-control study involving 414 patients and 1199 cancer-free controls to investigate whether single nucleotide polymorphisms (SNPs) in the WDR4 gene are associated with Wilms tumor susceptibility." (PMID 37283791, 2023). "Herein, our results suggested that WDR4 gene SNPs predispose patients to Wilms tumor." (PMID 37283791, 2023). "However, the relationship between polymorphisms in the WDR4 gene and susceptibility to Wilms tumor remains to be fully investigated." (PMID 37283791, 2023). "Finally, the study focused only on the relationship between WDR4 gene SNPs and Wilms tumor risk." (PMID 37283791, 2023). "To date, although there have been no studies on the direct effect of WDR4 on the risk of Wilms tumor, our results suggested that the WDR4 rs6586250 T genotype may increase the susceptibility to Wilms tumor by increasing WDR4 gene expression." (PMID 37283791, 2023).